INS (insulin)
Diseases named in the same sentence as INS in open-access papers (continued):
Sharing a sentence is not in itself a finding about the gene and the disease.
metabolic syndrome (continued). "Other metabolic indicators, such as insulin, lipids, metabolomics, and indirect calorimetry, have also been used to assess metabolic flexibility and were found to be predictive of body weight, metabolic syndrome, T2D, and CVDs." (PMID 38439744, 2024). "HFD‐induced metabolic syndrome in rats is mediated by activating GSK3β which reduce insulin sensitivity, and using of GSK3β inhibitor lithium can reverse these metabolic alterations." (PMID 39644152, 2024). "The disruption of these pathways can lead to weight gain, an elevated blood pressure, impaired insulin sensitivity, and dyslipidemia." (PMID 38892514, 2024). "Associating CMD-risk phenotypes include triglycerides, glucose, total cholesterol and LDL cholesterol, as well as insulin treatment and a metabolic syndrome diagnosis following harmonized criteria." (PMID 39217505, 2024). "Lifestyle modifications, such as a calorie-restricted diet, regular aerobic and resistance exercise, as well as behavioral therapy, form the cornerstone of treatment, aiming to reduce visceral adiposity, improve insulin sensitivity and ameliorate dyslipidemia." (PMID 39407722, 2024). "In laminitis-prone ponies on summer pastures and in horses with metabolic syndrome after insulin infusion, it has been observed that there is an increase in blood pressure." (PMID 38396558, 2024). "The frequency of the metabolic syndrome in participants considered insulin-resistant, i.e., the lowest quartile of eGDR by the Williams, Duca, and Januszewski eGDR formulae, was 64, 71, and 64%, respectively." (PMID 38702680, 2024). "From the timeline map of keywords, we found that studies have focused on insulin sensitivity, prediabetic high-risk diseases (polycystic ovary syndrome (PCOS), coronary artery disease, dyslipidemia) and lifestyle interventions." (PMID 38241546, 2024). "First, even if the prevalence of metabolic syndrome was similar in men and women, fasting glycemia was higher in men—suggesting greater insulin resistance." (PMID 38421551, 2024). "Increased physical activity can improve insulin sensitivity and aid in weight management, addressing two key components of metabolic syndrome." (PMID 39770936, 2024). "IR is characterized by damaged insulin sensitivity in the target tissues of insulin (adipose tissue, liver, and skeletal muscles) and plays a crucial role in impaired glucose homeostasis, metabolic syndrome, and T2D." (PMID 39138413, 2024). "For example, hyperthyroidism can lead to increased insulin resistance and hepatic steatosis, while hypothyroidism can contribute to dyslipidemia and greater lipid accumulation in the liver." (PMID 39685066, 2024). "Multiple investigations have assessed the substantial impact of insulin resistance surrogate indices on various health-related conditions, such as vascular damage, hypertension, and metabolic syndrome." (PMID 39744182, 2024). "Previous studies have shown that lifestyle interventions combining PA and nutrition are effective in reducing BMI, blood pressure, low-density lipoprotein cholesterol, and other cardiometabolic risks such as metabolic syndrome and insulin sensitivity." (PMID 39203786, 2024). "Insulin resistance and metabolic syndrome: Individuals with PCOS have abnormal insulin secretion and function." (PMID 38779261, 2024). "Post hoc analysis identified improvements in insulin sensitivity and glucose metabolism in a subset of participants with metabolic syndrome." (PMID 38347627, 2024). "The gut microbiota composition at baseline was shown to mediate the improvement in insulin sensitivity in FMT-treated metabolic syndrome." (PMID 39064765, 2024). "Some studies indicate that IER, including TRE, can reduce HOMA-IR and fasting insulin levels in overweight individuals or those with metabolic syndrome." (PMID 39327619, 2024). "Improving insulin sensitivity can reduce the risk of developing T2DM, a common consequence of metabolic syndrome." (PMID 39770936, 2024).
metabolic syndrome (continued). "Several studies demonstrated that besides reduced glucose uptake, insulin resistance and hyperglycemic conditions also alter cellular lipid metabolism, leading to the development of dyslipidemia in mammals." (PMID 38916917, 2024). "Insulin plays a crucial role in regulating lipid metabolism, and disruptions in insulin signaling pathways can lead to dyslipidemia." (PMID 38659523, 2024). "Another interesting approach is represented by FMT: persons with metabolic syndrome who underwent the procedure experienced improved insulin sensitivity and dyslipidemia, even though some authors do not agree." (PMID 39200110, 2024). "Increasing the expression of proteins involved in glucose transport, insulin signaling pathway, and dyslipidemia is another mechanism by which bioactive compounds of cinnamon administer their antidiabetic effects." (PMID 39021815, 2024). "Metformin cures dyslipidemia by lowering high levels of insulin in the blood or free fatty metabolism by the liver." (PMID 38779261, 2024). "Excessive hepatic gluconeogenesis promotes excessive lipid synthesis in insulin-resistant hepatocytes and is an important factor in the development of dyslipidemia." (PMID 39519809, 2024). "This is in accordance with the higher prevalence of dyslipidemia in general with aging and related changes in metabolism, insulin sensitivity hormones, hormonal and body composition." (PMID 38933885, 2024). "The presence of the mutant bb genotype of the BsmI SNP was associated with lower serum 25(OH)D3 levels, which is considered to be an indirect effect of BsmI on the metabolic syndrome, given the role of vitamin D in regulating insulin secretion and sensitivity." (PMID 37175993, 2023). "Compositional changes in the overall gut microbiota are significantly dependent on several markers related to metabolic syndrome, including body weight, glucose–insulin homeostasis, endotoxemia-induced inflammation, and intestinal barrier integrity." (PMID 37445955, 2023). "Resistance for insulin, dyslipidemia, hypertension, abdominal adiposity, and chronic stress are the underlying factors." (PMID 38248733, 2023). "Several studies have demonstrated that short-chain fatty acids (SCFAs) are the main metabolites of gut microbiota that play a critical role in regulating metabolic syndrome and maintaining energy homeostasis and host insulin sensitivity." (PMID 36966186, 2023). "In the present study, MHO individuals were not only free form metabolic disorders such as elevated blood pressure, elevated blood glucose, and dyslipidemia, but also were insulin sensitive." (PMID 37304121, 2023). "Individuals with metabolic syndrome who were heterozygous for the FokI SNP had higher iPTH levels (a marker for induction of insulin secretion) and higher β cell secretion (HOMA β) than individuals without this polymorphism." (PMID 37175993, 2023). "In one study, obese individuals with metabolic syndrome experienced an improvement in insulin sensitivity 6 weeks after receiving FMT with microbiota from lean donors." (PMID 37280680, 2023). "The glucagon to insulin ratio was a significant predictor of metabolic syndrome even after adjusting for confounders through multiple regression analysis." (PMID 37762748, 2023). "In this review, we summarize the evidence of TAARs’ contribution to the metabolic syndrome pathogenesis and regulation of insulin secretion in pancreatic islets." (PMID 38002300, 2023). "Both insulin and thyroid hormones are affected by autoimmune pathology, are part of the metabolic syndrome, and affect cellular metabolism." (PMID 36926020, 2023). "Metabolic syndrome (MetS) (also known as syndrome X or insulin resistance syndrome) is a multicomponent disease characterized by central obesity, lipid and insulin dysregulation, and hypertension." (PMID 36647030, 2023). "It is also involved in the regulation of insulin sensitivity, a factor that is part of the so-called metabolic syndrome." (PMID 37238961, 2023).
metabolic syndrome (continued). "The narrative is rounded out by the dysregulation of postprandial lipid metabolism in insulin resistance states and consequent CVD risk, the clinical evaluation of postprandial dyslipidemia, current research limits, and potential future study directions." (PMID 38303975, 2023). "In preclinical animal models, POA improves glucose intolerance, dyslipidemia, and steatosis of the muscle and liver, while improving insulin sensitivity and secretion." (PMID 38313838, 2023). "In the present study, we discovered that metformin significantly improved abnormal lipids, glucose, and insulin sensitivity in ob/ob mice, confirming its future therapeutic potential for metabolic syndrome." (PMID 37860765, 2023). "Metabolic syndrome (MetS) includes a cluster of metabolic disorders characterized by elevated insulin levels, excessive body weight, hypertension, and dyslipidemia." (PMID 37767256, 2023). "The study included patients with a diagnosis of metabolic syndrome, and clinical factors such as body mass index, lipid profile, insulin resistance, and blood pressure were recorded." (PMID 38022144, 2023). "L-Carnitine has been demonstrated to have anti-inflammatory and antioxidant properties, as well as to improve insulin sensitivity and dyslipidemia." (PMID 36984764, 2023). "All in all, our results point to the importance of proper nutrition (including breastfeeding and balanced diets) during early life to preserve insulin sensitivity and protect not only against metabolic syndrome but also cognitive impairment." (PMID 38203399, 2023). "MoC E included BMI screening, waist–hip ratio, ultrasound to assess for non-alcoholic fatty liver disease, and screening for metabolic syndrome, including a 2-hour oral glucose tolerance test, insulin, and lipid profile." (PMID 37614710, 2023). "Several reports point to the anti-natriuretic effect of insulin (e.g., insulin-mediated enhanced salt absorption in the kidney) as a major mechanism responsible for the development of hypertension in metabolic syndrome." (PMID 36901725, 2023). "The fasting glucagon to insulin ratio was significantly lowered as the number of metabolic syndrome components increased." (PMID 37762748, 2023). "These curcumin derivatives modulated adipogenesis, lipid metabolism, insulin resistance, steatosis, lipotoxicity, inflammation, oxidative stress, endoplasmic reticulum stress, apoptosis, autophagy, fibrosis, and dyslipidemia to a greater extent than curcumin." (PMID 37762669, 2023). "An ongoing phase I clinical study (NCT02469272) examining small intestinal microbiota transfers from lean to obese subjects has shown improved insulin sensitivity in patients with metabolic syndrome as well as improved insulin sensitivity in those with NASH." (PMID 37513787, 2023). "Patients with metabolic syndrome showed increased insulin sensitivity after six weeks of infusion of gut microbiota from lean individuals." (PMID 37056675, 2023). "Many studies showed a relationship between elevated prolactin levels and the resistance of peripheral tissues to insulin, obesity/overweight, atherogenic dyslipidemia and metabolic syndrome." (PMID 37176648, 2023). "In our study, individuals with metabolic syndrome had a significantly lower glucagon to insulin ratio." (PMID 37762748, 2023). "Dyslipidemia can affect the function of the pancreas and other organs by influencing insulin secretion and peripheral insulin sensitivity." (PMID 37990237, 2023). "In the present study, not only human subjects but also a pre-clinical monkey model of metabolic syndrome were involved to address the correlation between tryptamine/phenethylamine and insulin resistance for several reasons." (PMID 37591886, 2023). "It was further associated with the development of metabolic alterations including the onset of metabolic stress, dyslipidemia, and decreases in insulin sensitivity and glucose control." (PMID 37813884, 2023).
metabolic syndrome (continued). "AgeAccelENCen40 + is correlated with markers of inflammation, metabolic syndrome, and C-reactive protein (bicor = 0.08 and P = 8.8 × 10−11) and insulin levels (bicor = 0.09 and P = 1.7 × 10−5)." (PMID 36964402, 2023). "A similar relationship was found between serum carotenoids (lycopene, lutein, and β-carotene) and fasting serum insulin and the metabolic syndrome." (PMID 37507876, 2023). "Pegbelfermin treatment for 12 weeks improved dyslipidemia and insulin sensitivity, increased adiponectin levels, and decreased ALT, AST, and Pro-C3 levels in obese patients with T2D." (PMID 37260446, 2023). "According to research on insulin-resistant individuals, low vitamin D serum concentrations are associated with lower HDL-C levels, causing HDL-C dyslipidemia." (PMID 37764823, 2023). "The measurement of insulin concentration has some difficulties, such as the cross-reactivity of proinsulin, the type of insulin radioimmunoassay kit used, blood sampling with heparin, hemolysis, and the state of dyslipidemia." (PMID 37241071, 2023). "A relationship is thus described between the degree of hepatic triacylglycerol (TG) accumulation and the occurrence and severity of metabolic syndrome components, elevated hepatic glucose production, and reduced insulin clearance by the liver." (PMID 37591342, 2023). "Consistent with previous reports, the current study showed that HF diet-fed rats developed adiposity, elevated glucose, insulin resistance, leptin resistance, dyslipidemia and increased expression of I-FABP in the small intestine." (PMID 37237272, 2023). "Synbiotic supplementation in metabolic syndrome patients significantly improved insulin, FBS, QUICKI, and HOMA-IR." (PMID 37929031, 2023). "Regarding Blautia, it is an acetate producer, which can impulse insulin release and promote metabolic syndromes such as hyperglyceridemia, fatty liver disease, and insulin resistance." (PMID 36901634, 2023). "Cluster 3 appeared to be the most insulin resistant and most treated for dyslipidemia, in spite of the highly abundant metabolome in lysophospholipids and sphingomyelins." (PMID 36862673, 2023). "In the presented study, we have found that SHBG mitigates ER stress and improves cells viability and insulin sensitivity in adipose-derived mesenchymal stem cells (ASC) isolated from metabolic syndrome-affected horses (EMS)." (PMID 37697311, 2023). "These events create conditions that promote inflammation, induce endothelial dysfunction, and reduce insulin sensitivity, which leads to further inflammation, dyslipidemia, hyperglycemia, and other cardiometabolic dysfunction." (PMID 37396171, 2023). "At baseline, the LOW KCAL group was older, had higher glucose and insulin levels, and had a greater proportion of participants meeting metabolic syndrome criteria compared to the LOW CHO and LOW FAT diet groups (all ps < 0.001)." (PMID 37599685, 2023). "Insulin plays an important role in metabolic syndrome during aging, and defects in the regulation of insulin signaling lead to a variety of metabolic diseases, including NAFLD." (PMID 37893085, 2023). "A 2-hour oral glucose tolerance test including insulin levels and lipid profile was used to screen for dysglycemia, hyperinsulinemia, and dyslipidemia, respectively." (PMID 37614710, 2023). "In particular, chronic inflammation due to RA alters insulin resistance, body composition, and lipid profiles, and these metabolic changes lead to a metabolic syndrome that mediates premature atherosclerosis." (PMID 36787310, 2023). "The first was found enriched in HFD-fed mice following treatment with prebiotics, which improved insulin sensibility and protected them from hepatic steatosis and dyslipidemia, and a similar outcome was found in ob/ob mice given inulin." (PMID 37111688, 2023).
metabolic syndrome (continued). "Studies in animal models indicate that treatment with doses within the range of human exposure decreases insulin sensitivity and glucose tolerance, induces dyslipidemia, and modifies functional β-cell mass and serum levels of insulin, leptin, and adiponectin." (PMID 37134142, 2023). "Previous reports in which diets with high sugar in drinking water induced MS have demonstrated changes in glucose homeostasis and insulin, oxidative imbalance, low-grade inflammation, and plasma dyslipidemia." (PMID 37887410, 2023). "Heightened concentrations of C-reactive protein are directly related to body mass index, abdominal circumference, high blood sugar and resistance to insulin in persons diagnosed with metabolic syndrome." (PMID 38248733, 2023). "In hierarchical logistic regression analysis, the fasting glucagon to insulin ratio significantly contributed to metabolic syndrome even after adjusting for other covariates." (PMID 37762748, 2023). "The fasting glucagon to insulin ratio was significantly lower in patients with metabolic syndrome (14.0 ± 9.7 vs. 17.3 ± 10.3, p < 0.05)." (PMID 37762748, 2023). "Altogether these results suggest that DI induced the development of dyslipidemia and reduced insulin sensitivity and glucose tolerance." (PMID 37813884, 2023). "The dysregulation of postprandial lipid metabolism in insulin resistant states and subsequent CVD risk, the clinical evaluation of postprandial dyslipidemia, present research constraints, and potential subsequent study directions round up the narrative." (PMID 38303975, 2023). "Elevated insulin, glucose, and free fatty acid level, after HGI meal consumption, can induce IR which can, in turn, cause dyslipidemia." (PMID 36782338, 2023). "Several cross-sectional epidemiologic studies consistently showed that circulating prolactin levels positive correlated with increased insulin sensitivity, lower glucose and lipid levels, and lower prevalence of T2D and metabolic syndrome." (PMID 36993818, 2023). "Cardiovascular ageing and disease are associated with an accelerated risk due to physical and physiological traits next to menopause, including dyslipidemia, resistance to insulin, redistribution of adipose tissue, and systemic hypertension." (PMID 38288203, 2023). "A gut microbiota transplantation study on humans revealed that gut microbiota from lean donors increased the insulin sensitivity in obese recipients with metabolic syndrome." (PMID 36651735, 2023). "In this investigation, a higher number of metabolic syndrome components correlated with an elevated glucagon to insulin ratio." (PMID 37762748, 2023). "IR, or the impaired insulin action, that is, irresponsiveness to the insulin in adipose tissues, muscles, liver and other tissues, represents an important component of the pathophysiology of metabolic syndrome." (PMID 37754255, 2023). "At the same time, a large number of studies have shown that Akk bacteria can also promote GLP-1 secretion, insulin sensitivity, and intestinal microecological richness, and plays an important role in the treatment of metabolic syndrome." (PMID 37063280, 2023). "The worsening of FBG levels was the most prominent change among the changes in the metabolic syndrome components; it implied an adverse change in insulin resistance during the social distancing period." (PMID 37654163, 2023). "Dyslipidemia and hypertriglyceridemia in particular are highly responsive to variables such as diet, changes in body weight, insulin sensitivity, and sympathetic tone." (PMID 36890393, 2023). "Six weeks after infusion of microbiota from lean male donors, the insulin sensitivity of male rehabilitants with metabolic syndrome increased along with the level of butyrate-producing gut microbiota." (PMID 38068759, 2023).